HYAL6P (hyaluronidase 6, pseudogene)
Synonyms: HYAL6; formerly HYALP1
Gene: Unitary pseudogene on chromosome 7 (123,814,139 to 123,829,252, forward strand). Ensembl gene ENSG00000228211.
Diseases named in the same sentence as HYAL6P in open-access papers:
HYAL6P is named in the same sentence as 3 diseases in open-access papers, as found by Europe PMC text mining. Sharing a sentence is not in itself a finding about the gene and the disease.
HYAL6P shares sentences with these, for which no sentence is quoted: diffuse large B-cell lymphoma (1 paper); glioma (1); ovarian carcinoma (1).